KEAP1 (kelch like ECH associated protein 1)
Diseases named in the same sentence as KEAP1 in open-access papers (continued):
Sharing a sentence is not in itself a finding about the gene and the disease.
cancer (continued). "Therefore, Keap1/Nrf2 pathway activation is associated with a poor prognosis in many cancers." (PMID 30735010, 2019). "Similarly, PALB2 (partner and localizer of BRCA2), a binding partner of BRCA2 (breast cancer type 2 susceptibility protein), was found to directly interact with KEAP1 and induce NRF2 nuclear accumulation followed by antioxidant gene expression in HEK293 and U2OS cells." (PMID 31097977, 2019). "Previous reports found that aberrant Keap1/Nrf2 pathway activation due to Kelch‐like ECH‐associated protein 1 (Keap1) mutations or Nuclear factor E2‐related factor 2 (Nrf2) mutations induced resistance of cancer cells to chemotherapy and accelerated cell growth via the supply of nutrients." (PMID 30735010, 2019). "In addition to LUAD, KEAP1/NRF2 mutations are found in other cancers." (PMID 28967864, 2017). "KEAP1 mutations lead to constitutively active Nrf2 and subsequent protection of cancer cells from chemotherapeutic drugs, constitutive activation of Nrf2 is prominently expressed in various kinds of cancers, which has been shown to protect against cancer and leads to progression and poor survival." (PMID 24386210, 2013). "However, some studies examining activating mutations in NRF2 or loss of function of KEAP1 in human cancers, such as esophagus, skin, and ovarian cancers, did find one or more of these mutations altering the NRF2 pathway, which suggests protumorigenic involvement in these extrapulmonary tissues." (PMID 23577226, 2013). "As an impaired Keap1-Nrf2 system is induced by mutation or hypermethylation in several types of human cancer, we hypothesized that mutation or epigenetic changes of KEAP1 may decrease Keap1 expression and increase Nrf2 activity and transactivation of its downstream genes in CRC." (PMID 22325485, 2012). "Impressively, the CDDO-Me treatment decreased tumor size across all cancer cell lines (decrease compared to vehicle: WT = 73%, KEAP1 KO = 91%, NRF2 KO = 77%), maintaining volumes less than 300 mm3 10 days post-treatment initiation." (PMID 41462606, 2025). "In human cancers of the lung, esophagus, head and neck, liver, and bladder, high levels of NRF2 activating mutations, NRF2 copy number amplifications or KEAP1/CUL3 loss-of-function mutations are observed." (PMID 40027760, 2025). "DNA methylation of KEAP1 has been more frequently studied than NFE2L2 across multiple cancer models, revealing distinct methylation patterns at KEAP1 promoter region when comparing normal and tumor lung tissues." (PMID 40563292, 2025). "While our study is a proof of concept for treatment efficacy of triterpenoids in a KEAP1-mutant cancer setting, some limitations in our model exist." (PMID 41462606, 2025). "To test this model that NRF2 plays an important role in the promotion of G12Ci-induced anti-cancer immunity, we treated WT and Keap1-Nrf2 DKO cells with G12Ci and measured NISP chemokine gene induction in cells without a KRASG12C mutation." (PMID 40890297, 2025). "Drugs targeting the NRF2 pathway also frequently block downstream antioxidant genes that support cancer cell survival or prevent the pathway’s interaction with KEAP1, a negative regulator of NRF2." (PMID 40563292, 2025). "According to eleven pan-cancer sequencing studies on 101,679 samples from 100,611 patients, NRF2, KEAP1, and CUL3 mutation took place in 1.8%, 4%, and 1.3% cases, respectively." (PMID 40507333, 2025). "Examples of the microenvironmental conditions influencing the dual effects of Nrf2 in cancer include overexpression of the GSTP1 enzyme, Keap1 mutations, loss of heterozygosity, and hypoxia/reoxygenation." (PMID 41415550, 2025). "One mechanism of NRF2 activation in cancer involves the disruption of the KEAP1-NRF2 interaction through the binding of competitive disruptor proteins to KEAP1." (PMID 39941813, 2025).
cancer (continued). "It follows that KEAP1 KO cancer cells induce a metabolic shift in macrophages to promote lipid metabolism, and therefore they decrease anti-tumor immune activating capabilities." (PMID 41462606, 2025). "Methylation studies have revealed significant changes in KEAP1 epigenetic patterns in cancer cells from lung and other sides, mainly at CpG sites level at 5′ end, where the main KEAP1 CpG island was located." (PMID 40563292, 2025). "M2-macrophages were increased in tumors generated by the orthologous transplantation of KEAP1 mutant LL2 cancer cells compared with those generated by WT LL2 cells." (PMID 41035689, 2025). "We surmise that as NRF2-activated cancer cells have an ability to suppress immune cell infiltration into tumors, circulating immune cells tend to accumulate more in WT 3LL tumors than in KEAP1-KO 3LL tumors in the bilateral model." (PMID 41035689, 2025). "In contrast, another research showed that in multiple kinds of cancer, LKB1 or KEAP1 co-mutation tended to be accompanied by KRASG12C rather than other types of KRAS mutations." (PMID 40611261, 2025). "To examine this point experimentally, in this study, we established a mouse model of NRF2-activated cancers using the transplantation of syngeneic cells harboring Keap1 and Nrf2 gene modifications." (PMID 41035689, 2025). "Before measuring how activated OT-I CD8+ T-cells kill their OVA-MC38 target cells, we exposed them to culture medium conditioned by cancer spheroids harboring WT or Keap1 KO macrophages." (PMID 41176316, 2025). "This review provides an overview of the KEAP1 competitive protein interactors identified thus far and explores their involvement in cancer development." (PMID 39941813, 2025). "This study demonstrates that NRF2 activation, either through pharmacological inhibition of KEAP1 or genetic mutations, leads to an imbalance in the NADH/NAD+ ratio, which disrupts mitochondrial function and sensitizes cancer cells to Complex I inhibition." (PMID 40563292, 2025). "KEAP1 is a key component of the Nrf2-Keap1 signaling pathway, which in both normal and cancer cells serves to protect from environmental toxins, including chemotherapy." (PMID 40647516, 2025). "In many cancers, NRF2 is constitutively activated due to mutations in KEAP1, overexpression of NRF2, or aberrant oncogenic signaling, leading to enhanced antioxidant defenses." (PMID 40746900, 2025). "In HCC and other cancers, mutations or abnormal expression of KEAP1 or NRF2 lead to sustained activation of this pathway, contributing to cancer cell survival, proliferation, and resistance to therapy." (PMID 40818321, 2025). "According to a recent pan-cancer whole genome analysis, non-small cell lung cancer has the highest mutation frequency in both KEAP1 and NFE2L2 (ICGC/TCGA Pan-Cancer Analysis of Whole Genomes Consortium, 2020)." (PMID 40394395, 2025). "It is increasingly evident that the NRF2/KEAP1 pathway contributes significantly to the metabolic reprogramming of cancer cells by means of a transcriptional program that promotes cancer cell proliferation and malignant development." (PMID 40439888, 2025). "The expressions of NRF2 target gene Nqo1 and Gsta4 were also downregulated in the DKO 3LL cell line, demonstrating successful reversal of NRF2 hyperactivation in the KEAP1-KO cancer cells." (PMID 41035689, 2025). "We bilaterally transplanted the KEAP1-KO and WT cancer cells into right and left flanks of albino C57BL/6 mice, respectively, and compared the tumor immune microenvironment in the same host immune conditions." (PMID 41035689, 2025). "Cancers frequently achieve overexpression of NRF2 and these resulting phenotypes via somatic loss-of-function mutations in KEAP1." (PMID 41573641, 2025).
cancer (continued). "Mutations in KEAP1, hypoxic environment, along with epigenetic and post-translational alterations, lead to persistent NRF2 activation, enhancing cancer cells’ antioxidant capabilities and metabolic flexibility." (PMID 41333220, 2025). "RNA-sequencing of TE-BMDMs cultured in KEAP1 KO compared to WT cancer-conditioned media had enhanced tumor-promoting phenotypes, which reversed with CDDO-Me treatment." (PMID 41462606, 2025). "The Cancer Genome Atlas consortium and other sequencing projects have found that the KEAP1-NRF2 degradation pathway is frequently altered in cancer, by either gain-of-function mutations in NRF2 or loss-of-function mutations in KEAP1 or CUL3." (PMID 40470216, 2025). "Inactivating mutations in KEAP1 or activating mutations in NRF2 are frequently found in a number of cancers, including cancers of the lung, gallbladder, and liver." (PMID 40209947, 2025). "Collectively, we associated the redox status mediated by loss-function mutations of KEAP1 or STK11 to immune evasion and immunotherapeutic resistance by suppressing STING/MDA5 expression and interferon signaling of cancer cells." (PMID 41378285, 2025). "One of the means of NRF2 activation in cancer is through the binding of competitive protein interactors to KEAP1, which blocks the KEAP1-mediated ubiquitination of NRF2 and its degradation in the 26S proteasome." (PMID 39941813, 2025). "For instance, FGF5 derived from cancer-associated fibroblasts can activate FGFR2 on tumor cells, initiating downstream Keap1/Nrf2/HO-1 signaling and enhancing resistance to ferroptosis." (PMID 40867889, 2025). "Myeloid cells were increased in tumors generated by the transplantation of KEAP1 mutant LKR10 cancer cells compared with those generated by WT LKR10 cells." (PMID 41035689, 2025). "Biochemically confirmed competitive protein interactors of KEAP1 with putative involvement in cancer progression through the activation of NRF2 activity." (PMID 39941813, 2025). "KEAP1 KO cancers were previously found to have increased macrophage CD206 and therefore to promote tumor immunosuppression through the generation of M2-like macrophages." (PMID 41462606, 2025). "In advanced cancers, persistent NRF2 activation—through KEAP1/NFE2L2 mutations or oxidative adaptation—drives epithelial-to-mesenchymal transition, metabolic reprogramming, and immune evasion, promoting tumor invasion (T) and metastasis (M)." (PMID 41470226, 2025). "Keap1 knockdown mice show reduced growth of induced tumors but higher tumorigenicity in transplanted Keap1−/− cancer cells." (PMID 41008623, 2025). "Analyses of these transplanted cancer tissues revealed that the immune cell infiltration is significantly decreased in the KEAP1-deleted/NRF2-activated tumors." (PMID 41035689, 2025). "By contrast, this study established the mouse model that recapitulates the clinical phenotypes of low-level immune cell infiltration into NRF2-activated tumors using syngeneic 3LL cancer cells harboring genetic manipulations in Keap1 and Nrf2 genes." (PMID 41035689, 2025). "Cancer-associated fibroblasts (CAFs), for instance, secrete FGF5, which binds to FGFR2 on NPC cells and activates the Keap1–Nrf2–HO-1 axis." (PMID 40867889, 2025). "A prominent example is DNA methylation within CpG islands of the KEAP1 promoter, which is frequently hypermethylated in various cancers, resulting in suppressed KEAP1 expression and the aberrant activation of Nrf2." (PMID 40422216, 2025). "In assessing the cancer-mediated regulation of macrophages, we found KEAP1 KO LL2 cancer cells promoted the differentiation of the M2-like alternatively activated phenotype at the RNA level." (PMID 41462606, 2025).
cancer (continued). "Mutations in KEAP1 impede its ubiquitin ligase activity toward SOX9, promoting cancer cell growth and tumorigenesis by stabilizing SOX9." (PMID 40240356, 2025). "Of the currently 487 LUSC samples in TCGA (Pan-cancer Atlas), 21% have PTEN mutations (around 100 patients); but only 10 samples exhibit PTEN and NFE2L2 mutations and only 8 show PTEN and KEAP1 co-existing mutations." (PMID 40676628, 2025). "Compared to the existing reports, we firstly revealed its pro-cancer effects on regulating adipocyte lipolysis via KEAP1/NRF2 signaling." (PMID 41255573, 2025). "Strategies like downregulating NRF2 through siRNA transfection or overexpressing KEAP1 have shown potential in making resistant cancer cells more responsive to treatment." (PMID 41333220, 2025). "The anti-tumor potential of cells within the TIME, particularly macrophages, is potentiated by triterpenoid treatment in cancers with wild-type KEAP1 status." (PMID 41462606, 2025). "Taken together, these observations indicate that KEAP1 KO cancer cells promote a pro-tumor macrophage phenotype at a magnitude greater than the LL2 WT cells." (PMID 41462606, 2025). "It has been demonstrated that curcumin activates Nrf2, improving the effectiveness of cancer treatments by increasing heme oxygenase-1 (HO-1) and decreasing the Nrf2 inhibitor Keap1." (PMID 39456414, 2024). "Inhibits cancer formation.Allows nuclear Nrf2 translocation by disrupting its interaction with KEAP1." (PMID 39769005, 2024). "Although both CA and MMF can activate the Nrf2/ARE pathway by inducing Keap-1-Nrf2 dissociation, which results in Nrf2 protein stabilization, CA has been shown to promote proteasomal degradation of other proteins in cancer cells." (PMID 38396960, 2024). "Nrf2/Keap1/ARE pathway plays a major role in cancer prevention by anti-inflammatory effects, and reducing oxidative stress to reduce DNA damage." (PMID 39407193, 2024). "Decreased infiltration of lymphoid cell lineages, with some indication macrophages are also decreased, have been detected in human KEAP1 mutant cancers." (PMID 38542481, 2024). "Recent studies demonstrate that KEAP1 downregulates PD-L1 expression in cancer cells via ubiquitination and proteasome-mediated degradation and that overexpression of KEAP1 enhances cytotoxic T cell activation in vivo." (PMID 39596025, 2024). "KEAP1 mutations induce constitutive activation of NRF2, which protects cancer cells from chemotherapeutic drugs." (PMID 39000120, 2024). "This was supported by an independent study which reported that CB-839 augmented radiation response in a rodent xenograft model of NSCLC established by injection of a KEAP1-mutant cancer cell line." (PMID 39695143, 2024). "Through creation of the clonally derived LL2 lines, we identified large changes in the cytokine secretome of KEAP1 KO cancer cells." (PMID 38542481, 2024). "To validate the sensitizing effect of KEAP1 mutation or deficiency on AURKA inhibitors, we initially analyzed the sensitivity of NSCLC cell lines with wildtype or mutant KEAP1 to AURKA inhibitors in the Cancer Drug Sensitivity Genomics database GDSC." (PMID 38521813, 2024). "As another anti-cancer agent, dihydrotanshinone I can increase Nr2 degradation by Keap1 and it impairs Nr2 phosphorylation by PKC to reduce proliferation of gallbladder tumor." (PMID 39286246, 2024). "The discovery of the Keap1-Nrf2 signalling pathway will help to study the effect of DDW on cancer more accurately and facilitate further research on the tumour suppressor mechanism of DDW in the future." (PMID 38732643, 2024). "In summary, we have identified deleterious cancer-cell intrinsic changes facilitated directly by KEAP1 KO." (PMID 38542481, 2024). "In order to assess the interplay between KEAP1 and PD-L1 in cancer cell proliferation and tumorigenesis, we established cell lines with PD-L1 knockdown and those with simultaneous knockdown of both KEAP1 and PD-L1 in H1299." (PMID 38413563, 2024).
cancer (continued). "Our data suggesting KEAP1 KO cancer cells increase the recruitment of immune cells, in combination with evidence of increased CD206+ presence in the microenvironment, warranted further investigation." (PMID 38542481, 2024). "In this review, we delve into the cellular and molecular roles played by Gal-1 in the context of oxidative stress onset in cancer cells, particularly focusing on its involvement in activating the Nrf2/Keap1 signaling pathway." (PMID 38434765, 2024). "Our future directions include validation of prostaglandin signaling in human tumors, assessing direct M2 polarization by PGE2 derived from KEAP1 KO cancer cells, and assessment of the overall TIME in human NSCLC." (PMID 38542481, 2024). "Mutations in NRF2‐activation and KEAP1 preventing NRF2 repression occur in multiple types of cancer, such as liver cancer and lung cancer, leading to persistent activation of NRF2 in cancer cells." (PMID 38576456, 2024). "Nrf2/Keap1/ARE pathway aids in cancer cell growth and proliferation by promoting detoxification and antioxidant defense." (PMID 39407193, 2024). "It is evident that Nrf2/Keap1/ARE pathway plays a major role in cancer prevention by anti-inflammatory effects and reducing oxidative stress to reduce DNA damage leading to tumorigenesis." (PMID 39407193, 2024). "In cBioportal database, we analyzed KEAP1 mutations in NSCLC from a total of 6887 patients in 20 different studies, including TCGA pan-cancer atlas." (PMID 38184997, 2024). "In sight of this, Nrf2-inhibiting and Keap1-enhacing agents are being investigated to overcome this obstacle in cancer therapy." (PMID 39456749, 2024). "In NSCLC, KEAP1 and NFE2L2 mutations are highly prevalent, making the KEAP1-NRF2 signaling pathway one of the most commonly altered pathways in these cancers." (PMID 38184997, 2024). "Because CXCL1 was highly and consistently upregulated in our KEAP1 KO cell lines, this cytokine is likely to drive the presence of M2-like macrophages in these cancers." (PMID 38542481, 2024). "It is worth noting that mutations in both KEAP1 and NRF2 are common in many cancers and are associated with a poor prognosis." (PMID 38247494, 2024). "Owing to the dual nature of ROS in cancer, NRF2 and its antagonist, Kelch-like ECH-associated protein 1 (KEAP1), have become subjects of debate regarding their precise roles in either preventing or, conversely, promoting tumor progression." (PMID 38247494, 2024). "The studies described here evaluate the immune regulating capability of KEAP1-mutant cancer cells and how they further promote immunosuppression through the polarization of macrophages." (PMID 38542481, 2024). "Somatic mutations in the Nrf2 gene, KEAP1, and the E3 ubiquitin-ligase complex CUL3 have been recognized in many types of cancer, and these mutations are responsible for Nrf2 activation." (PMID 39309448, 2024). "Altogether, these data indicate that 4-OI operates independently of the NRF2/KEAP1 axis and ROS to promote VSVΔ51 infection in cancer cells." (PMID 38750019, 2024). "The NRF2 is a key regulator of the cell’s adaptative response to radical oxidant species and xenobiotics through the interaction with its negative regulator, Keap1, and contributes to cancer development, progression, and chemoresistance." (PMID 38791966, 2024). "Usually, in the cytoplasm, Nrf2 (Nuclear factor erythroid 2-related factor 2 (Nrf2) and Keap1 (Kelch-like ECH-associated protein 1) bind each other and cause proteasomal degradation resulting in antioxidant activity, detoxification, and cancer prevention." (PMID 38336617, 2024). "To gain further insights into the potential mechanism of KEAP1 in cancer progression, we conducted an initial analysis using Gene Set Enrichment Analysis (GSEA)." (PMID 38413563, 2024).